RARG (retinoic acid receptor gamma)
Diseases named in the same sentence as RARG in open-access papers (continued):
Sharing a sentence is not in itself a finding about the gene and the disease.
cancer (48 papers, 1999 to 2026). A tumor composed of atypical neoplastic, often pleomorphic cells that invade other tissues. "Pre-chemotherapy screening for this variant, along with RARG agonist treatment, suggested potential cardioprotection in cancer patients." (PMID 41446145, 2025). "Another notable GWAS identified that a non-synonymous coding variant in retinoic acid receptor gamma (RARG), rs2229774, was associated with anthracycline-induced cardiotoxicity in a paediatric cancer cohort." (PMID 40076674, 2025). "Overexpression of RARγ is associated with cancer cell proliferation." (PMID 37569466, 2023). "Regarding the widespread influences of RARγ and miR-30-5p, there is the capacity to change gene expression to many aspects of the control of cancer stem cell behavior, including the hallmark circuits that include for viability, proliferation, differentiation, cytostasis, and motility." (PMID 37569466, 2023). "Finally, a nominal significant association was found for rs2229774 in RARG and cancer treatment induced cardiac dysfunction." (PMID 36536332, 2022). "Aberrant expression of Retinoic acid receptor γ (RARγ) is implicated in cancer development." (PMID 27756432, 2016). "Thus, loss of RARγ may facilitate a shift toward a more cancer stem cell-like state, potentially contributing to increased tumorigenic and invasive potential in OCSCC." (PMID 41274504, 2025). "We further investigated the expression patterns of RARγ isoforms in various types of human cancer cells." (PMID 39744424, 2025). "Nonetheless, further studies are warranted to explore the broader applicability of RARγ inhibitors in other cancer models and to investigate their potential synergistic effects when combined with existing cancer immunotherapies." (PMID 40807274, 2025). "Ectopic overexpression of RARγ in cancer cells enhances cell proliferation, and downregulation reduces cell proliferation." (PMID 40362593, 2025). "In this study, we found that RARγ1, 2, 4 are the predominant RARγ isoforms expressed in various types of human cancers, including HNC." (PMID 39744424, 2025). "First, we provide a comprehensive overview regarding the expression of RARγ isoforms in human cancers." (PMID 39744424, 2025). "This review examines the influence of RARγ on the behaviour of normal and cancer cells and the proposed oncogenic roles of RARγ." (PMID 40362593, 2025). "In either case, they are dependent on RARγ signalling whereby targeting RARγ provides a means to growth arrest and kill cancer cells as follows." (PMID 40362593, 2025). "RARγ is expressed by cancer stem cells and is a targetable drive of cancer cell growth and survival." (PMID 40362593, 2025). "Our results demonstrated that RARγ isoform 1, 2, 4 are the predominant RARγ isoforms expressed in various types of human cancer cells, including HNC." (PMID 39744424, 2025). "Support for a role for RARγ in promoting the proliferation of cancer cells has been provided from knockdown and knockout studies." (PMID 38928275, 2024). "To examine this in our cancer models, we compared the expression of RARα, RARβ, RARγ, RXRα, RXRβ and RXRγ in AB1-HA tumors, which are sensitive to combination tretinoin–CY therapy, and AE17, CT26 and WEHI164 tumors, which are resistant." (PMID 38350880, 2024). "Why the cancer stem cells died via necroptosis when treated with very low doses of the RARγ and pan-RA antagonists is surprising and yet to be resolved." (PMID 39273194, 2024). "First, RARγ plays a key role in regulating the behavior of stem cells and, therefore, there is the prospect of controlling cancer stem cells (CSC)." (PMID 38928275, 2024). "When studying the per-ligand involvement, retinoids exhibited the highest mean receptor expression in the cancer cell lines of the small intestine, consistent with the high expression of RARG in the same cells." (PMID 39766077, 2024).
cancer (continued). "A concentration of 5 nM AGN205728, close to its ED50 for RARγ of 3 nM, prevented colony formation by the cancer stem cell (CSC)-like cells of the PCa cell lines." (PMID 39273194, 2024). "Findings from knockdown and knockout studies have provided further support to the view that RARγ promotes cancer cell proliferation, for example, from studies of colorectal and pancreatic cancer cells." (PMID 39273194, 2024). "RARγ is an oncogene, and the findings that overexpression within cancer cells correlated with a rapid disease progression and poor prognosis fits well with RARγ, ensuring the stemness of cancer stem cells." (PMID 39273194, 2024). "For example, findings from in vitro studies have shown that the use of an RARγ antagonist kills cancer stem cells and avoids the unwanted side effects of ATRA." (PMID 38928275, 2024). "It is important to bear in mind that there is still a paucity of information regarding a direct comparison of RARγ-mediated events within cancer stem cells versus their normal stem cell counterparts." (PMID 37569466, 2023). "The agents that target RARγ have been shown to be more active against cancer cells than their normal tissue counterpart cells." (PMID 36768694, 2023). "RARβ mRNA was either undetectable or present at low basal levels while RARα and RARγ mRNAs were each expressed at readily detectable basal levels in these examined cancer cell lines." (PMID 37689790, 2023). "These multiple influences are all germane to understanding how RARγ overexpression deregulates the behavior of cancer stem cells." (PMID 37569466, 2023). "Together, these findings provide a rationale for a clinical trial investigating an RARγ agonist to augment check point blockade response in cancers." (PMID 37689790, 2023). "The RARγ antagonist and 637A induced necroptosis, a failsafe cell death mechanism, which is important because some cancer cells are resistant to undergoing apoptosis." (PMID 37569466, 2023). "There is a knowledge gap that currently exists as to how the RAR subtype-selective retinoids like the RARγ agonist IRX4647 or the RARα antagonist IRX6696 affect cancer immunity." (PMID 37689790, 2023). "This review examines perturbations to the uptake, storage, and metabolism of retinoids and particularly the action of RARγ within cancer cells." (PMID 36768694, 2023). "Our studies presented new insights into RARγ signaling in PDAC, but they are associated with several limitations: all of our experimental designs in this study focused only on cancer cell-autonomous functions associated with proliferation." (PMID 37198667, 2023). "This knowledge gap is examined here by elucidating the consequences of treatment with a novel RARγ agonist on the growth of syngeneic murine cancer models." (PMID 37689790, 2023). "That all-trans-retinol metabolism is deregulated within cancer cells and that RARγ is an oncogene within various cancers provide good support for targeting the retinoic acid pathway to eradicate cancer cells." (PMID 36768694, 2023). "Impaired ATRA synthesis coupled to overexpression of RARγ within cancer cells are features that have been attributed to normal stem cells." (PMID 37569466, 2023). "Targeting ATRA synthesis and RARγ has provided promising approaches to eliminating cancer stem cells because such agents have been shown to drive cell death." (PMID 37569466, 2023). "Findings from studies of RARγ knockdown and knockout within cancer cells have provided support to a role in promoting cell proliferation." (PMID 37569466, 2023). "Our study used TCGA and GTEx database to calculate RARG expression in ovarain cancer tissues and normal ovarian tissues." (PMID 36523991, 2022). "Addressing these questions should provide answers regarding the importance of RARγ in cancer initiation and/or disease progression." (PMID 33807298, 2021). "The action of antagonists of RAR on multiple cancer types provides strong support to the notion that RARγ possesses oncogenic potential." (PMID 33807298, 2021).
cancer (continued). "The RARγ antagonist (MM11253) was able to impair the effect of ATRA treatment in cancer stem cell population." (PMID 33723318, 2021). "In the mouse testicular embryonal carcinoma cell line, RA induces Bmp2 while simultaneously repressing Bmp4, specifically through RARα and RARγ." (PMID 34292881, 2021). "While these data support miR-96 targeting of RARγ, other studies have identified additional targets in prostate and other cancers including the pioneer factor FOXO1." (PMID 30120411, 2019). "In our current study, RARγ was identified by screening the shRNA library targeting cancer-related genes and this library of 1841 shRNAs targets 1,272 human genes, in which none of the known necroptosis-related genes is included." (PMID 28871172, 2017). "A lot of efforts have been made to explore the regulatory mechanism of RARγ in cancer, but there are contradictory views regarding its role in cancer." (PMID 27756432, 2016). "Taken together, these results strongly indicated that RARγ plays a pivotal role in cancer development." (PMID 27756432, 2016). "Emerging evidence suggests that aberrant expression of nuclear receptor RARγ contributes to cancer development and progression." (PMID 27756432, 2016). "Pharmacologic activation of RARα, or inhibition of RARγ activity, reduces cancer cell growth in vitro, thereby suggesting that a specific RARα agonist would be a more effective method of cancer treatment than an RAR pan-agonist such us ATRA." (PMID 22920668, 2012). "Expression of RARα, RARβ, RARγ, RXRα and RXRβ was found in most cell types in gastric mucosa tissues from normal individuals as well as in distal normal tissues from cancer patients." (PMID 10389997, 1999). "RARγ agonism or overexpression enhanced the proliferation of cancer cells." (PMID 41683719, 2026). "As RARγ controls the behaviour of both normal and cancer stem cells, it is important to consider the extent to which normal cells might be affected when targeting RARγ to kill cancer cells." (PMID 40362593, 2025). "We next examined whether such an RARγ-targeting approach could also be a valid strategy for the treatment of various human cancers other than HNC." (PMID 39744424, 2025). "Cancer cells appear to be more sensitive to the targeting of RARγ than normal cells." (PMID 40362593, 2025). "For RARγ-targeting, in addition to the increasingly popular RNA-based approaches 36, pharmacological antagonism of RARγ is another appealing strategy to achieve RARγ-targeting cancer therapy." (PMID 39744424, 2025). "Our results indicate that RARγ-targeting approach could be a promising therapeutic and chemopreventive strategy for human cancers." (PMID 39744424, 2025). "In contrast to RARβ2 and RARα, the role of RARγ in human cancers is yet to be defined." (PMID 39744424, 2025). "In this case, targeting RARγ presents an effective avenue to the treatment of cancer." (PMID 38928275, 2024). "Decreases in β-catenin target gene expression may be relevant to the ability of the RARγ antagonist to kill cancer cells." (PMID 39273194, 2024). "As above, antagonism of RARγ was highly effective in killing cancer stem cells." (PMID 38928275, 2024). "RARγ is also an oncogene, and antagonism of RARγ, or all RARs, kills cancer cells." (PMID 38928275, 2024). "There are two main rationales to the use of an RARγ antagonist to treat cancer." (PMID 38928275, 2024). "Therefore, dysregulation of an individual RAR is most likely to be seen for diseases, for example, overexpression of RARγ in a wide range of cancer cells." (PMID 38928275, 2024). "Furthermore, RARγ is an oncogene for some of the cancers that have a low intracellular level of ATRA." (PMID 37569466, 2023). "Hence, there should be differential usage of RARγ within cancer cells that have or are expected to have a low intracellular level of ATRA." (PMID 37569466, 2023).
cancer (continued). "Whilst there is still some uncertainty regarding the status of ATRA synthesis and signaling within normal tissue-specific stem cells, there is a difference between the sensitivity of cancer cells and normal cells to agents that target RARγ and prevent ATRA synthesis." (PMID 37569466, 2023). "It is interesting to speculate whether RARγ plays a role in restricting the fate of cancer stem cells so that they produce an overwhelming abundance of lineage-restricted, unwanted, and antisocial cells." (PMID 37569466, 2023). "Therefore, there seems to be a failure to switch off RARγ expression when PCa CSCs mature to give rise to the population of overt cancer cells." (PMID 36204679, 2022). "RARγ is selectively expressed within stem cells and their immediate offspring, it plays a crucial role in the survival of these cells, and is an oncogene for a number of cancers." (PMID 35563205, 2022). "It is shown that synthetic retinoid WYC‐209 overcomes the limitation of conventional anticancer drugs by activating retinoic acid receptor gamma exit from nucleus to induce tension‐abrogation‐mediated chromatin decondensation and DNA damage to effectively kill malignant tumors." (PMID 36031407, 2022). "Further support to targeting RARγ to eliminate CSCs is that RARγ is an oncogene for some cancers." (PMID 36204679, 2022). "In this regard, RARγ is an oncogene for a number of cancers." (PMID 35563205, 2022). "Alternatively, it is important to bear in mind that RARγ provokes epigenetic changes within stem cells and that epigenetic signatures are increasingly considered as important to cancer, cell responsiveness to chemotherapeutics, and targeting therapeutic interventions." (PMID 33807298, 2021). "Here, we examine evidence that supports the view that RARγ is an Achilles heel for some cancers." (PMID 33807298, 2021). "Cancer cell lines with higher levels of MSLN indeed showed a trend toward higher levels of RARG." (PMID 32616712, 2020). "Moreover, alterations in the expression or activity of specific retinoic acid receptors (RARA, RARB, and RARG) were well-known TFs controlling transcription and inducing diverse types of cancer by recruiting different co-regulator complexes." (PMID 29033978, 2017). "Recent studies implicate RARγ in cancer development and progression." (PMID 27756432, 2016). "Moreover, integrating RARγ-targeted approaches with existing immunotherapeutic strategies may offer synergistic benefits in cancer treatment." (PMID 40807274, 2025). "Similarly, targeting RARγ could also be an effective treatment in other human cancers, as demonstrated in our current findings and results from previous studies 30-33." (PMID 39744424, 2025). "Thus, to our knowledge, the current study is the first to demonstrate—in human PDAC specimens—that RARγ was overexpressed in the nucleus of cancer cells and that the expression of RARγ increased during the progression of PDAC, including PanIN, a precancerous lesion of PDAC." (PMID 37198667, 2023). "Hence, the frequencies of cancer stem cells for many cancers may be an underestimate, and there is a need to measure the levels of ATRA and RARγ within cancer stem cells versus their normal stem cell counterparts." (PMID 37569466, 2023). "On one hand, RARγ may function as an oncogene to drive cancer cell growth and metastasis." (PMID 27756432, 2016). "In contrast, RARγ5 was expressed only in the non-cancer breast epithelial (MCF10A) and cervical epithelial (Z183A and Z172) cell lines, suggesting that this shift in RARγ isoform expression is a common feature of human cancers." (PMID 39744424, 2025). "This study aims to decipher the role of RARγ isoforms in carcinogenesis and progression of HNC, and to explore the feasibility of RARγ-targeting approach as a therapeutic and/or chemo-preventive strategy for HNC and other types of human cancers." (PMID 39744424, 2025).
cancer (continued). "As seen for RARγ, YAP is an oncogene for several cancers, showing elevated expression in bladder, cervical, colon, gastric, non-small-cell lung, esophageal, and ovarian cancers." (PMID 39273194, 2024). "We also identified 5 genes (LGR4, RARG, PNISR, PCOLCE2, RALGDS) that shared the same patterns across three types of cancer, and 39 genes with two overlaps across eight cancer types." (PMID 32764426, 2020). "Given that RARγ contributes to HCC invasion and metastasis, we investigated that the effect of RARγ on EMT, a critical event in cancer cell invasion and metastasis." (PMID 27756432, 2016). "Taken together, our results indicate that RARγ-targeting approach could be a promising therapeutic and chemo-preventive strategy for HNC and other types of human cancers." (PMID 39744424, 2025). "To explore this, we tested whether knocking down RARγ isoforms using specific shRNAs could suppress the growth-promoting effect in HNC and various cancer cells." (PMID 39744424, 2025). "RARγ-targeting approach could be a promising therapeutic and chemopreventive strategy for treatment of HNC and other types of human cancers." (PMID 39744424, 2025). "Additionally, several motifs were found to be specifically disrupted in certain cancer types, such as M2321_1.02 (TP63) in Bone-Osteosarc, M6446_1.02 (RARG) in Breast-AdenoCA, and M5371_1.02 (EGR4) in Lymph-CLL." (PMID 37782656, 2023). "It is not entirely clear how deregulations of ATRA-, RARγ-, and miR-30-5p-mediated events lead to the abnormal behavior in cancer stem cells and their progeny." (PMID 37569466, 2023). "Targeting RARγ, by the AGN205728 and LY2955303 antagonists and acacetin, and interference with ATRA synthesis, by 637A, DIMATE, NCT-501, silybin, and solomargine, were effective against cancer stem cells." (PMID 37569466, 2023). "The RARγ antagonist and pan-RAR antagonist are promising new cancer therapeutics." (PMID 35563205, 2022). "Retinoic acid receptor γ (RARG), which is 90% homologous to retinoic acid receptor α (RARA) and retinoic acid receptor β (RARB), is unique among the three RAR subtypes because it typically resides in the cytoplasm of cancer cells." (PMID 36523991, 2022). "Interestingly, while pharmacological antagonism of RARγ can drive necroptosis in cancer stem cells, mouse skin keratinocytes lacking RARγ are resistant to DNA damage-induced necroptosis." (PMID 41274504, 2025). "Finally, through both in vitro and in vivo models, we demonstrate that RARγ-targeting strategy could be a promising therapeutic and chemopreventive approach for both HNC and various kinds of human cancers." (PMID 39744424, 2025). "CD437 induced apoptosis in several cancer cell types independent of RARγ activation." (PMID 38928275, 2024). "Genetic overexpression of RARG, or treatment with the RARG agonist, CD1530, was found to improve cell viability and function without diminishing the anti-cancer efficacy of doxorubicin in human cells and mouse models." (PMID 38359791, 2024).
adenocarcinoma (1 paper, 2024). A common cancer characterized by the presence of malignant glandular cells. "Notably, direct inhibitory effects of RARγ activation on this pathway has been reported to limit cell apoptosis in adenocarcinoma cells." (PMID 38926848, 2024).
infection (1 paper, 2023). The state of being infected such as from the introduction of a foreign agent such as serum, vaccine, antigenic substance or organism. "Many LCM-associated regulons were not altered by infection (C/EBPβ), while others were lost (RARG and MAF) and others gained (KLF4, STAT3, FOSB, and BHLHE40)." (PMID 36948193, 2023).